CD86 (CD86 molecule)
Diseases named in the same sentence as CD86 in open-access papers (continued):
Sharing a sentence is not in itself a finding about the gene and the disease.
tumor (continued). "M1 macrophages (CD86+ and CD80+) release pro-inflammatory cytokines (e.g., IL-6, IL-12, TNF-α) to play an anti-tumor role, while M2 macrophages (CD206+) release pro-tumor cytokines (e.g., IL-4, IL-10, IL-13) to promote tumor progression and metastasis." (PMID 35432300, 2022). "Herein, we aimed to detect the expression of CTLA-4, CD86, CD4, and CD8 in surgical specimens from RC patients after nCRT/nCT, and to classify CD4+ and CD8+ cells into stroma, tumor, and invasive categories according to their location." (PMID 36428666, 2022). "The main cell clusters included T cells (CD3E and CD3D), B cells (CD19), natural killer cells (NCAM1, FCGR3A and KLRD1), myeloid cells (CD86 and CD163) and tumor cells (EPCAM, KRT8 and KRT18)." (PMID 36497182, 2022). "In our work, we also demonstrated the capacity of combined treatment to enhance the CD86 expression in CD11c+MHCII+ dendritic cells and CD11b+MHCII+F4/80+ macrophages into the tumor, accompanied by a decrease in the number of CD11b+Gr-1hi MDSCs." (PMID 34975315, 2022). "Accordingly, efficient activation (CD86+, CD40+) of DCs (CD45+CD11c+) and CD8+ T (CD45+CD3+CD8+) cells-mediated inhibition of tumor growth occurred." (PMID 36559246, 2022). "Mice treated with doxorubicin alone or combination treatment had lower expression of tumor PD-L1, CTLA-4, Foxp3, and tumor-infiltrating dendritic cell (CD86) proteins than did controls, with the lowest expression in mice co-treated with high-FO/Se." (PMID 36483592, 2022). "Tumor tissues were removed from CT26 tumor-bearing mice and double-stained with F4/80 and CD86 (to detect M1-type macrophages) or with F4/80 and CD206 (to detect M2-type macrophages)." (PMID 36246355, 2022). "In tumor tissue, the presence of CD206+ macrophages (M2-like) dropped from nearly 80% to 40%, while CD86+ macrophages rose from around 20% to 40%." (PMID 36291890, 2022). "Further, PTT with aFn14-PBNP resulted in a unique tumor cellular immunophenotype consisting of thermal dose-dependent enhanced expression of CD137L, CD80, CD86, and CD40." (PMID 35957076, 2022). "The mRNA expression of the M1 (iNOS and CD86) and M2 markers (ARG1 and CD206) in tumor tissue was analyzed by RT‐qPCR." (PMID 34861103, 2022). "In the CD4+T cell population analyzed, PRI revealed two bin-plot patterns (CD90/CD44/CD86 and CD90/CD44/CD27) and 20 bin plot features for threshold-independent classification of mice concerning ineffective and effective tumor treatment." (PMID 35592315, 2022). "Tumor cells are also able to escape from NK lysis due to their lack of expression of costimulatory molecules, such as B7-1 (also known as CD80), B7-2 (or CD86), CD40 and CD70, that hinder the optimal activation of these cells." (PMID 35335881, 2022). "PD-1, which binds to PD-L1, also known as CD274, or to PD-L2/CD273, is a peripheral immune checkpoint of immune, tumor, and stromal cells, whereas CTLA-4 binds to CD80/CD86, also known as B7-1/B7-2 co-stimulatory receptors, on antigen-presenting cells (APCs)." (PMID 35159208, 2022). "Specifically, DCs function in immunotherapy by presenting tumor antigens to naïve T cells, and exosomes secreted from DCs contain CD80 and CD86 that are required for naïve CD4+ T-cell activation." (PMID 36119094, 2022). "The high correlation of HMOX1 with CD86 and PDCD1 LG2 also suggests that interactions between tumor cell ferroptosis and immune cells need to be studied in more detail." (PMID 34975326, 2022). "After cryo-thermal therapy, compared to that in the tumor-bearing control group, the expression level of MHC-II on MDSCs was upregulated, and the level of CD86 was downregulated." (PMID 36389684, 2022). "It promotes tumor growth via angiogenesis and inhibits GADC maturation by downregulating costimulatory factors CD80 and CD86, which are necessary to produce robust anti-tumor immune responses." (PMID 35711434, 2022).
tumor (continued). "Tumor immune cells (PTPRC/CD45+) also consisted of B cells (MS4A1/CD20+), plasma cells (XBP1+), macrophages (CD14+), dendritic cells (CD80+, CD86+), and mast cells (TPSAB1+)." (PMID 35742914, 2022). "We also performed IHC staining on both Pan02 subcutaneous and KPC orthotopic tumour tissues to examine the expression level of various markers of immune activation, including CD8, granzyme B, CD62L, CD49b and CD86." (PMID 35174623, 2022). "At first, in order to attack and eliminate tumor cells, APCs, via CD28-CD80/CD86 pathway, activate T cells, but at the same time regulate pro-inflammatory mechanisms, activating inhibitory pathways by immune checkpoints." (PMID 35656508, 2022). "Tumor treatment with decitabine also resulted in increased levels of MHC and costimulatory molecules (CD80, CD86, and CD40) essential for DC antigen presentation function." (PMID 35992806, 2022). "On the other hand, tumor cells also reduce the expression of CD80 and CD86 and increase the expression of inhibitory molecules such as PDL-1, which neutralizes TIL-dependent antitumor responses." (PMID 36389779, 2022). "We found that CSF-1R was significantly correlated with tumor-related immunosuppressive molecules including PDCD1, CTLA4, CD80, CD86, HAVCR2, etc.." (PMID 35444953, 2022). "Our results showed that DCs cocultured with Smad4KO tumor cells showed higher levels of CD80+ and CD86+ cells than those cocultured with WT tumor cells." (PMID 35064757, 2022). "Tumor cell co-stimulatory or co-repressor signaling, involving genes such as CD28, CD80, CD86 and CTLA4, plays a critical role in regulating cell proliferation, differentiation and cytokine secretion." (PMID 36465397, 2022). "Co-culture of the virus-infected cells with TILs, upregulation of MHC I, MHC II, and costimulatory receptors, such as CD80 and CD86 on tumor cells and increased the IFN-γ-secreting cells, leading to delayed tumor growth and improved survival time." (PMID 36389779, 2022). "Tumor uptake of both radiopharmaceuticals is more expressed in tumor edge regions, with greater intensity at 2 weeks, as demonstrated by [11C](R)-PK11195 autoradiography and immunofluorescence with TSPO antibodies and CD86 pro-inflammatory phenotype." (PMID 36559209, 2022). "In both tumor models, CD11b+F4/80hi TAM that coexpress high levels of CD206 also showed significantly high expression of costimulatory receptors CD86 and ICOSLG compared with the CD11b+F4/80dim TAM population." (PMID 35503656, 2022). "Previous studies have demonstrated that up-regulation of CD80 and CD86 in the tumor vaccine systems can successfully improve the immunogenicity of vaccines due to the effect of costimulatory CD80 and CD86 molecules on tumor immunity." (PMID 36466863, 2022). "Both tumor-bearing CD4+ T cells and cryo-thermal CD4+ T cells promoted the expression of CD86 in DCs and macrophages, but only cryo-thermal CD4+ T cells significantly upregulated the expression of MHC II in macrophages." (PMID 35874660, 2022). "The homogenized tumor cells were stained with macrophage markers, that is, CD45R, F4/80 along with surface markers specific for M1(CD86) and M2(CD206) phenotype." (PMID 34689394, 2022). "Further understanding of the impact of chemo(radio)therapy on the tumor microenvironment, particularly the CTLA-4 and CD86 signatures, is required to optimize the design of clinical trials." (PMID 36428666, 2022). "Some M1 markers (IL1A, IL1B, CD86), M2 markers (CCL18, MRC1/CD206, CSF1R), and TAM markers (HLA-DR, IL1RN, CD163, ITGAM, SIGLEC1/CD169) were highly expressed on both tumor and non-tumor macrophages." (PMID 33918618, 2021). "Among all tested combinations, the triplet of OX40L, CD80 and CD86 mRNA induced the strongest anti-tumor immunity in subcutaneous A20 and CT26 tumor-bearing mice." (PMID 33858437, 2021).
tumor (continued). "VPA/HPTA treatment alone significantly promoted an increase in the cell population expressing M1 marker (CD86; P <0.01) and M1 function markers (IL-12, IL-6, MHC-II, IFN-γ and TNF-α; P <0.01) at the transcriptional level in the tumor." (PMID 34054811, 2021). "As the CD86/CD163 ratio increases, CRC patients potentially exhibit a decreasing incidence of tumor recurrence." (PMID 34512652, 2021). "We then examined the changes in M2-like TAM markers (CD163, CD206, CD209, IL-10 and Arginase 1) and M1-like TAM markers (CD80, CD86, IL-12, and TNFα) induced by CM from ILT4-downregulated tumor cells." (PMID 33537094, 2021). "In tumor-burden BALB/C mice, ferric citrate (2.5 mg per three day, totally 17.5 mg) injection promotes reactive oxygen species (ROS) production and CD86 expression of tumor infiltrating macrophages, and lowers the volume and weight of H22 hepatoma xenograft." (PMID 34054839, 2021). "Classically activated (M1) TAMs, which express increased levels of iNOS, CD86, and CD169, play resistant roles in tumor progression and metastasis." (PMID 34512652, 2021). "Experiments in a murine model revealed that T cell costimulatory molecules such as CD80/CD86 are increased in tumor infiltrating immune cells after cisplatin treatment, suggesting that CD80/CD86 expression can be modulated by cisplatin treatment." (PMID 33802033, 2021). "However, CD86 also is readily expressed on tumor cells, for reasons which to date remain unknown." (PMID 34768877, 2021). "As the CD86/CD163 ratio increases, CRC patients also potentially exhibit a decreasing incidence of tumor recurrence." (PMID 34512652, 2021). "Furthermore, immunosuppressive molecules B7-H3, CD86, and CD38 as well as necroptosome components cleaved caspase-8 and RIP3 (also known as RIPK3) were relatively underexpressed in ASPcKO tumors suggesting less immune surveillance in the tumor microenvironment with Pten loss." (PMID 34535684, 2021). "We observed that ILT4 knockdown in tumor cells decreased M2-like markers, including CD163, CD206, IL-10, and Arginase 1 but increased M1-like markers including CD80, CD86, IL-12, and TNFαin TAMs." (PMID 33537094, 2021). "In this study, we consistently observed high expression of both HLA-DR and CD40 by most tumor-infiltrating B cells, as well as CD80, CD83, and CD86 expression by a subset of B cells." (PMID 33763071, 2021). "The population of CD80+CD86+ cells in DiD positive macrophages of Oxa(IV)@Lip@M were counted to be ~70%, which was similar to that of LPS treated M1 cells, while blank BMMs only counted to be ~37%, indicating that the drug loaded macrophages could retain their M1 phenotype in the tumor tissue." (PMID 34262026, 2021). "The multivariate regression analysis showed an independent prognostic value of CD86 in LGG on OS (HR = 1.678, 95%CI [1.308, 2.152], Cox P < 0.001) after variables including age, gender, and tumor grade were adjusted." (PMID 33954112, 2021). "Blockade of CTLA4 has been shown to increase the infiltrative T cell and decrease Treg response to tumor cells by allowing the co-stimulatory receptor CD28 to bind CD80 (B7.1) and CD86 (B7.2) expressed on antigen-presenting cells (APC)." (PMID 34976006, 2021). "The tumour cells can escape from the killing of T cells by activation of PD‐1/PD‐L1, CTLA4/CD80/CD86 and other immune checkpoints." (PMID 33325636, 2021). "On the other hand, serum butyrate levels limit the anti-tumor efficacy of anti-CTLA4 therapy in metastatic melanoma by restraining the up-regulation of CD80/CD86 on dendritic cells and ICOS on T cells, accumulation of tumor-specific T cells and memory T cells." (PMID 33708214, 2021). "An integrated gene profile and functional analysis of tumor-infiltrating immune cell (TIC) proportions revealed that DC activation markers (CD80, CD83, CD86) were positively correlated with CXCL8 expression." (PMID 34025668, 2021).
tumor (continued). "The expression of M1 macrophage markers iNOS, IL-1β, TNF-α and CD86 was increased, and the expression of M2 macrophage markers IL-10, Arg-1 and CD206 was reduced in the tumour tissues of tumour-bearing mice." (PMID 34726570, 2021). "In rat models with multiple implanted liver adenocarcinomas, the treatment for one tumor with laser ablation led to an increased expression of CD8, B7-2 (CD86), MHCII, LFA1 (CD11a), and ICAM1 (CD54) at the invasion front of another untreated tumor." (PMID 34830949, 2021). "Collectively, this analysis confirmed increased numbers of CD86+ antigen presenting cells and presence of macrophages, particularly in DFMO + PTI treated tumor-bearing mice, which was consistent with pathological assessments." (PMID 34945011, 2021). "We identified and verified that the expression levels of CYBB, CD86, and C3AR1 in tumor tissues were higher than those in normal tissues." (PMID 34950700, 2021). "According to CD86/CD163 ratio and tumor stage, stage II-III patients were stratified into four recurrence-risk subgroups (high-ratio stage II, high-ratio stage III, low-ratio stage II, and low-ratio stage III)." (PMID 34512652, 2021). "On the TIMER and THPA websites, it is verified that the expression levels of CYBB, CD86, and C3AR1 genes in tumor tissues were higher than those in normal tissues." (PMID 34950700, 2021). "These cDC1s and cDC2s had increased expression of CD86, MHC-II and CCR7, suggesting that these cells were highly activated and developed migratory potential towards the tumor-draining LN." (PMID 33408092, 2021). "One mechanism by which Treg suppress the anti-tumor response is by interaction of CTLA-4 with CD80/CD86 on DC leading to a reduced expression of MHC class II, CD40 and CD86 molecules, all being important for Treg maturation and activation." (PMID 34638420, 2021). "Consistently, our in vivo data show that Poly6 vaccination also led to a strong enhancement of CD40 expression in tumor infiltrated DCs compared to other DC costimulatory molecules (CD80, CD86, and MHC class II)." (PMID 33499256, 2021). "At the same time, the expression patterns of ZC3H12B, T cell markers CD4 and CD8, M1 type markers CD14 and CD86, and M2 type markers CD163 and CD206 were also detected in mouse tumor tissues." (PMID 33718596, 2021). "CTLA4 can be expressed by tumor cells or immune cells, including DCs, which inhibits T-cell activation by preventing CD80/CD86 on APCs from binding to CD28." (PMID 33732237, 2021). "Sarcoma data from the TCGA were downloaded to analyze the lncRNAs positively correlated with immune checkpoint inhibitory molecules (CD274, CD80, CD86, PDCD1 LG2 and LGALS9), which accelerate the process of tumor cell immune evasion." (PMID 34178688, 2021). "The AAA-CD4+ T cells also recruited significantly more host DCs and macrophages into the tumor, which expressed high levels of antigen-presenting molecules (MHC class II), co-stimulatory molecules (e.g., CD80 and CD86), and cytokines (IL-12 and IL-23)." (PMID 34625113, 2021). "We found that tumor-infiltrating CD33high cells showed high gene expression levels of CD36, CD14, FUT4 (CD15), CD80, CD86, CSF1R and immune checkpoint ligand genes including CD274 (PD-L1), LGALS9 (galectin-9), PVR and VSIR." (PMID 33000418, 2021). "The tumour-draining lymph nodes (TDLNs) of the treated mice were collected to investigate the DC maturation by flow cytometric analysis of CD80+ and CD86+, two biomarkers of mature DCs51." (PMID 33893275, 2021). "These tumor-infiltrating MHC class IIhigh DCs derived from AAA-CD4+ T cell-treated mice expressed high levels of CD80 and CD86 on their surface." (PMID 34625113, 2021). "The IPLD-treated mice had as high as 53.6% CD80+CD86+ mDCs in TDLNs compared with 24.6% in the PLD-treated mice and 11.0% in the PBS group, promoting the recruitment of T cells into the tumours." (PMID 33893275, 2021).
tumor (continued). "We developed a prognostic nomogram based on CD86/CD163 ratio and tumor stage that allows for individualized estimation of the 48-month RFS probabilities among stage II-III CRC." (PMID 34512652, 2021). "DC immune functions are impaired both in the circulation and at tumor sites in patients with EC, and this is accompanied by decreased CD80 and CD86 expression." (PMID 33995371, 2021). "Tumor cell suspension was stained with antibodies directed against the CD45, F4/80, CD86, CD206, antigens." (PMID 34526531, 2021). "Although the biology mechanism behind CD86/CD163 ratio is well known, the use of this ratio hasn’t been assessed for predicting tumor recurrence in CRC." (PMID 34512652, 2021). "Poly6 treatment also enhanced expression of DC maturation markers CD40, CD80, CD86, and MHC class II molecules in tumor and draining lymph node tissues in MC38-bearing mice." (PMID 33499256, 2021). "Our results are in line with previous studies showing increased tumor cell uptake and upregulation of maturation markers CD80 and CD86 on different subsets of human blood DCs after treatment with CDDP and OXA." (PMID 32560232, 2020). "In mice, butyrate restrains anti-CTLA-4-induced up-regulation of CD80/CD86 on dendritic cells and ICOS on T cells, accumulation of tumor-specific T cells and memory T cells." (PMID 32358520, 2020). "We examined the macrophages infiltration in tumors at 8-week when tumor acquired resistance to bevacizumab, whereas CD68+ CD206+ for classic M2 macrophage and CD68+ CD86+ for M1 macrophage." (PMID 33214550, 2020). "DCs isolated from several tumor models and cancer patients were found to possess tolerogenic properties, such as low levels of co-stimulatory molecules (CD80, CD86) and low production of Th1-polarizing cytokine IL-12." (PMID 33105813, 2020). "Taken as a whole, our study found at least three pathways, i.e., IL-6, CD86, and ICOSL, by which tumor B cells can contribute to Tfh activation and induce a potent microenvironment sustaining, in turn, FL cell growth." (PMID 33028033, 2020). "Exosomes carrying tumor-derived dsDNA from irradiated breast cancer cells increased expression of costimulatory molecules CD40, CD80, CD86 and initiated type I IFN production in DCs in a STING-dependent manner." (PMID 33238631, 2020). "Collectively, these data indicated that CD86 and CD206 had a prognostic value in predicting survival and tumor recurrence of ICC patients." (PMID 32002338, 2020). "Conditioned medium from high EGFR-expressing tumor cells treated with NB-PDT led to the maturation of human dendritic cells, as indicated by the upregulation of CD86 and MHC II on their cell surface, and the increased release of IL-12p40 and IL-1β." (PMID 32326519, 2020). "We further found that the numbers of CD11c+CD11b−CD103+H-2Kb+ DCs which expressed high levels of CD86, XCR1 and CD24 but low levels of CD64 were significantly reduced in tumor-burdened lungs of KP7 mice compared to KP mice." (PMID 33257678, 2020). "Our previous study reported that low presence of CD86+ M1 TAMs and high presence of CD206+ M2 TAMs were significantly correlated with aggressive tumor phenotypes and worse prognosis in HCC patients." (PMID 32002338, 2020). "We also observed that VV-iPDL1/GM significantly promoted tumor-infiltrating DC maturation, as evidenced by an increased expression of MHCII, CD80, CD86, and CD40." (PMID 32170083, 2020). "On days 7 and 14 after radiation, the expression levels of CD86+, CD4+, CD8+, and Foxp3+ cells, and levels of Ki-67+ protein were detected by immunohistochemistry, and the tumor necrosis rate was calculated." (PMID 32942998, 2020). "In terms of the surface expression quantitated through the median fluorescence intensity (MFI), CD86, CD80, and MHC-I expression on SM1 tumor cells markedly increased after INAPs-PTT (red) and ICG-PLGA-PTT (blue) treatment compared to controls in vitro." (PMID 31963449, 2020).